DEFB124 (defensin beta 124)
Description:
Has antibacterial activity.
Synonyms: DEFB-24
Tractability: Antibody: UniProt places it where antibodies can reach, with high confidence; UniProt predicts a signal peptide or a membrane-spanning region; its Gene Ontology location is reachable by antibodies, with medium confidence.
Gene: Protein-coding gene on chromosome 20 (31,465,471 to 31,476,757, reverse strand). Ensembl gene ENSG00000180383.
Subcellular location: Secreted
Pathways (Reactome):
Immune System: Beta defensins; Defensins
Gene Ontology:
Molecular function: protein binding
Biological process: innate immune response
Cellular component: extracellular region
Genetic constraint (gnomAD): Loss-of-function variants: 0 observed, 3.58 expected, observed/expected ratio (o/e) 0, 90% interval 0 to 0.83. That is too few expected variants to judge how well the gene tolerates losing a copy. Missense variants: 78 observed, 87.9 expected, observed/expected ratio (o/e) 0.89, 90% interval 0.74 to 1.07. Synonymous variants: 38 observed, 38.54 expected, observed/expected ratio (o/e) 0.99, 90% interval 0.76 to 1.29.
Homologues: Orthologues: chimpanzee DEFB124 (99% identical), rabbit DEFB124 (70% identical), dog DEFB124 (69% identical), guinea pig DEFB124 (68% identical), rat Defb25 (66% identical), mouse Defb25 (63% identical). Paralogues in human: DEFB135 (34% identical), DEFB121 (32% identical), DEFB132 (32% identical), DEFB128 (31% identical), DEFB118 (30% identical), DEFB119 (28% identical), DEFB115 (27% identical), DEFB123 (27% identical), DEFB127 (27% identical), DEFB116 (25% identical), DEFB125 (25% identical), DEFB134 (25% identical), and 7 more.